YY1 (YY1 transcription factor)
Diseases named in the same sentence as YY1 in open-access papers (continued):
Sharing a sentence is not in itself a finding about the gene and the disease.
cancer (continued). "In this paper, we discuss the regulation of YY1 overexpression in cancer cells, the role of YY1 in the maintenance of cancer resistance to cytotoxic drugs/cells and the role of YY1 in the regulation of anti-apoptotic gene products." (PMID 37686541, 2023). "The disruption of the NF-κB/YY1/Snail/RKIP loop in cancer cells reverses chemoresistance due to the inverse relationship between YY1 and RKIP." (PMID 37686541, 2023). "YY1 is a protein regulator of gene expression that has been shown to be involved in the progression of numerous cancers." (PMID 37686614, 2023). "This review discusses how YY1 overexpression regulates death protective proteins that control cancer cell resistance." (PMID 37686541, 2023). "Through several signaling pathways involving multiple interactions and cascades, it was found that RKIP targets the inhibition of YY1 and can be targeted for possible cancer treatments." (PMID 37686541, 2023). "By integrating multiple data sources and applying advanced computational methods, we aimed to identify novel insights into the role of RKIP and YY1 in cancer, as well as potential therapeutic targets and biomarkers." (PMID 37894300, 2023). "We constructed a univariate Cox proportional-hazard regression model to predict the prognostic risk of YY1 and PEBP1 in pan-cancer, and found that the two genes associate with the prognoses of various tumors." (PMID 37894300, 2023). "To further explore the mechanisms underlying the abnormal mRNA expression of YY1 and PEBP1, we explored the relationship between each gene’s CNV and their mRNA expression levels in pan-cancer." (PMID 37894300, 2023). "To better understand the potential implications of the cross-talk between RKIP and YY1 in cancer, we comprehensively analyzed different cancer types using bioinformatics approaches." (PMID 37894300, 2023). "Gain- and loss-of-function assays were employed in the scrutiny of the biological effects of the ALKBH5/YY1/ATG4B axis on cancer cell proliferation and invasion abilities in vitro." (PMID 37724907, 2023). "By integrating multiple data sources and applying advanced computational methods, we aimed to identify novel insights into the role of PEBP1/RKIP and YY1 in cancer, as well as potential therapeutic targets and biomarkers." (PMID 37894300, 2023). "The CRISPR/Cas9-mediated knockout acts on cancer cells, and it specifically targets and interferes with the YY1 gene." (PMID 37686541, 2023). "Our previous study demonstrated the essential roles of the circ‐CTNNB1/DDX3/YY1 axis in cancer progression." (PMID 36181462, 2023). "Due to its critical role in tumorigenesis, as well as its involvement with the progression, invasiveness, development and resistance of various cancers, YY1 serves as a prognostic marker and is the focus of cancer therapy as a potential target." (PMID 37686541, 2023). "These crosstalks involved the mitogen-activated protein kinase (MAPK)/PI3K pathways and the dysregulated nuclear factor-kappaB (NF-κB)/Snail/Yin Yang 1 (YY1)/RKIP/PTEN loop in many cancers." (PMID 37205308, 2023). "YY1 and CP2c is a transcription factor that regulates epigenetic pathways and protein modifications among several kinds of cancer." (PMID 37444605, 2023). "Our findings highlight that the transcription factor YY1 has the potential to promote or repress oncogenic proliferation in cancer cells depending on several factors." (PMID 37686541, 2023).
cancer (continued). "Overall, the analysis of multiple prognostic datasets pan-cancer revealed the cancers in which YY1 and PEBP1 significantly correlate with a good or bad prognosis, respectively." (PMID 37894300, 2023). "Most commonly, YY1 displays overexpression in various cancers and is positively correlated with the pathogenesis of cancer." (PMID 37686541, 2023). "Although YY1 was overexpressed in many cancers, the survival and prognosis analysis results of YY1 gene suggested that different conclusions will be drawn in different tumors." (PMID 35791393, 2022). "In this work, we analyzed the function of YY1 in various malignancies from a macro viewpoint in order to get a better knowledge of cancer etiology and enhance cancer detection and therapy." (PMID 35791393, 2022). "Yin Yang 1 (YY1) plays an oncogenic role through regulating the expression of various cancer-related genes and activating key oncoproteins." (PMID 35406384, 2022). "Accumulating evidence shows that YY1 is overexpressed in multiple cancer types and that increased YY1 levels correlate with poor clinical outcomes." (PMID 35103856, 2022). "We first explored the potential carcinogenic effect of YY1 in 33 cancers using the cancer genome atlas (TCGA) project and gene expression omnibus (GEO) datasets in this research." (PMID 35791393, 2022). "The protein expression of YY1 in 8 pairs of ESCA cancer tissues and adjacent tissues was detected by western blot." (PMID 35359580, 2022). "Taken together, YY1/DLEU1/miR-149-5p/YAP1 axis exerts crucial cancer-promoting function in CCA progression, and DLEU1 has potentiality as a biomarker or therapeutic target." (PMID 35864972, 2022). "The results showed that YY1 expression level in 12 cancer tissues was significantly negatively correlated with the expression level of most immune cells." (PMID 35791393, 2022). "This is parsimonious with the detrimental effects of YY1 in a number of diverse medical conditions, including cancers, where the melatonergic pathway is dysregulated." (PMID 36613794, 2022). "Ferroptosis functions remarkably in T cell-driven adverse outcomes of cancer cells, and HnRNPL inhibits Jurkat T cell-mediated Castration-Resistant Prostate Cancer (CRPC) cell ferroptosis through the YY1/PD-L1 axis, partially promoting cancer immune escape." (PMID 36335094, 2022). "Yin-Yang 1 (YY1) has a crucial function in the development of several malignancies, according to recent research." (PMID 35791393, 2022). "In several cancers, an inverse correlation between the pro-tumorigenic YY1 and the anti-tumorigenic RKIP has been observed." (PMID 35205667, 2022). "Emerging evidence shows that YY1 undergoes proteasome-dependent degradation in cancer and other cells." (PMID 35103856, 2022). "In this study, we aimed to aberrant expression of YY1 and its prognostic significance in human pan-cancer." (PMID 35791393, 2022). "Considering that YY1 overexpression is observed in many cancers and has various biological functions with respect to the hallmarks of cancer, it is an attractive approach to utilize YY1 as a novel target for therapeutic interventions." (PMID 36059990, 2022). "Consistently, increased YY1 expression has been observed in almost all cancer types compared to their cognate normal cells or tissues." (PMID 35406384, 2022). "The aim of this computational study is to assess the role of two important cancer factors, YY1 and RKIP as novel predictive biomarkers in LC." (PMID 35205667, 2022). "We should be aware of the influence of elevated YY1 expression on the diagnosis and treatment of these cancers and utilize this as a guide to enhance the diagnosis and treatment of associated tumors." (PMID 35791393, 2022). "More research into the mechanism of YY1 at the cellular and molecular levels will assist to elucidate its function in various cancers." (PMID 35791393, 2022). "Our first pan-cancer analysis offers a pretty comprehensive knowledge of YY1's oncogenic involvement in various cancers." (PMID 35791393, 2022).
cancer (continued). "While the emCpGs harbour enriched binding sites for their specific emTFs, the non-correlated CpGs shared a binding signatures for SP1, CTCF, NRF1, GABPA, KLF9, and YY1 providing a protective effect against de novo methylation across cancer types." (PMID 35440061, 2022). "The inhibitory effects of JAC1 on TNBC were due to its binding of YY1 therefore rescued anti-cancer functions of JWA gene via both G1 phase arrest and pro-apoptosis." (PMID 35383155, 2022). "Similar to the diverging roles of YY1 during healthy tissue development, also in cancer YY1 has been found to act as either transcriptional activator or inhibitor and its overall impact on malignant tissues can be pro-as well as anti-tumorigenic." (PMID 35693944, 2022). "Functional enrichment and protein network analysis can help us study the protein transcription factor network of YY1 in different cancers and then predict its mechanism of action." (PMID 35791393, 2022). "In cancer, YY1 and RKIP are interconnected and able to modulate each other’s expression in an inverse relationship, through several regulatory loops." (PMID 35205667, 2022). "YY1 mediates the expression of many genes involved in cell proliferation, differentiation, and apoptosis, and hence its role in cancer progression has been a topic of interest among researchers." (PMID 35408813, 2022). "The data strongly suggested that the YY1-regulated EZH2 activity plays a dominant role in promoting cancer progression." (PMID 35406384, 2022). "YY1 is a common essential gene as defined by the Cancer Dependency Map (DepMap), and MN cells containing YY1‐targeting sgRNAs and co‐expressing a Crimson (Crim) fluorescent reporter were depleted over time in culture." (PMID 35514210, 2022). "This information is consistent with our findings which show that HIF-1α positively regulates YY1 expression, and that several transcription factors are reportedly involved in chemoresistance of different types of cancer including ALL." (PMID 35163649, 2022). "The Gene Expression Profiling Interactive Analysis (GEPIA) website (gepia.cancer-pku.cn) showed that YY1 is positively correlated with METTL3 in AML samples from The Cancer Genome Atlas (TCGA) database." (PMID 36424383, 2022). "In summary, the expression of YY1 was statistically correlated with clinical prognosis, protein phosphorylation, and immune cell infiltration in our initial pan-cancer study." (PMID 35791393, 2022). "YY1 is overexpressed in variety types of human cancer including breast, colon, lung, glioma, bladder, and prostate, and plays essential roles in cell proliferation, cell viability, epithelial-mesenchymal transition, metastasis and drug/immune resistance." (PMID 35103856, 2022). "Our findings suggested YY1 as a novel prognostic biomarker for many tumors and an immune therapy response indicator in most cancer types." (PMID 35791393, 2022). "More and more evidence shows that YY1 transcription factor has become an important factor affecting the development and progression of cancer." (PMID 35359580, 2022). "EZH2 frequently functions as a partner of YY1 in silencing miRNAs in various cancer models and the oncoprotein binding domain of YY1 is crucial for its interaction with EZH2." (PMID 36497298, 2022). "YY1 is a transcription factor that is highly expressed in many cancers and is related to cell proliferation, survival and metabolic reprogramming." (PMID 35494016, 2022). "YY1 expression level was negatively correlated with B cell infiltration level in 12 kinds of cancer tissues." (PMID 35791393, 2022). "YY1 has been reported to activate many cancer-related genes, including MYC, HER2, FOS, SNAIL and TGFβ." (PMID 35406384, 2022).
cancer (continued). "YY1 is overexpressed and consequently correlates with poor prognosis in many types of cancer, and YY1 regulates a cohort of cancer-related genes." (PMID 36358822, 2022). "There is no an abundance of evidence that YY1 is overexpressed in multiple cancer types and that increased YY1 levels correlate with stronger malignant characteristics in many cancers." (PMID 34497757, 2021). "Next, we scrutinize evidence supporting the contributions of YY1 in CSCs from a number of various cancer types." (PMID 33728560, 2021). "YY1 is overexpressed in many types of cancer, and high expression correlates with poor clinical outcomes and resistance to chemotherapy and immunotherapy making it an attractive therapeutic target." (PMID 34597666, 2021). "Analysis of the data retrieved from an experimental protein database of cancer patient tissues enabled stratification of 17 types of cancer based on the expression patterns of YY1 and stem cell transcription factors." (PMID 33728560, 2021). "mTOR inhibition compromised CSC traits by modulating mitochondrial function in several types of cancers, such as pancreatic, ovarian, and bone cancers, suggesting that the YY1-mTOR-PGC-1α axis plays the key role in the biology of CSCs." (PMID 33728560, 2021). "YY1 is involved in the transcription of a variety of oncogenes and it, thus, participates in the regulation of cell cycle, apoptosis, and metastasis of cancer cells." (PMID 34933678, 2021). "Increasing studies suggest that YY1 functions as a tumor suppressor or a promoter in various cancer progression." (PMID 34818994, 2021). "YY1 was also shown to promote the expression of the stemness factor KLF4 and has been implicated in promoting the expression of stemness factors in cancer stem cells." (PMID 34115613, 2021). "Yin Yang 1 (YY1) is a key transcription factor that exerts functional roles in the cell biological process of various cancers." (PMID 34497757, 2021). "CSCs mirror the stemness properties of self-renewal and differentiation potential; thus, we describe the role of YY1 in the biology of embryonic and adult SCs as a biological framework to show the role of YY1 in CSCs in various cancer types." (PMID 33728560, 2021). "YY1 is a famous oncogene widely involved in the development of many cancers including hepatocellular carcinogenesis." (PMID 34215297, 2021). "YY1 is a transcriptional repressor known to have both cancer-promoting and cancer-inhibiting potential." (PMID 33450975, 2021). "The transcription factor, YY1, is a significant promoter of cancer and chemoresistance, including in GBM/GSC, although it can have some antitumour effects." (PMID 35582450, 2020). "Considering that YY1 overexpression is observed in many cancers and has various biological implications with respect to the hallmarks of cancer, it is an attractive approach to utilize YY1 as a novel target for therapeutic interventions." (PMID 32226547, 2020). "This intriguing finding is supported by earlier reports showing that Yy1, cMyc and Hsf1 orchestrate early developmental processes that cancer cells hijack during disease progression and metastasis." (PMID 32927726, 2020). "Immunostaining of candidate proteins MAX, TCF7L2, YY1, IRF1, STAT6, SP1, and E2F1 (selected based on qPCR results and/or associations to cancer in general) was performed in additional FTC specimens as outlined in the “Materials and Methods” section." (PMID 33063251, 2020). "Reconstitution experiments by knocking down YY1 under KrasG13V activation decreased KrasG13V-promoted cancer cell migration, proliferation and ZNF322A promoter activity." (PMID 32929330, 2020). "Regarding transactivation, circCTNNB1 promotes cancer progression by enhancing the transactivation of Yin Yang 1 (YY1) by DDX3 and thus upregulating target genes involved with β-catenin activation." (PMID 33317550, 2020). "In cancer cells, YY1 promotes cell cycle-related gene expression and promotes cell proliferation and invasion." (PMID 33235311, 2020).
cancer (continued). "YY1 is upregulated in many types of cancers and exerts its oncogenic effects through initiating, activating, or repressing the transcription of target genes." (PMID 33135346, 2020). "The evidence presented here reveals that the synthetic lethal interaction between miR-1193 inhibition and DNA-PKcs deficiency significantly suppresses cell growth and promotes apoptosis through the YY1AP1/YY1/FEN1 pathway in M059J cancer cells." (PMID 32732911, 2020). "microRNA-7 (miR-7) has been described as a negative regulator of several proteins involved in cancer, such as YY1 and KLF4." (PMID 33194748, 2020). "We performed transwell migration assay and tube formation of HUVECs cultured with the conditioned medium (CM) derived from cancer cells manipulated for YY1, ZNF322A and/or Shh expression level." (PMID 32929330, 2020). "Yin Yang 1 (YY1) is vastly expressed in several sorts of cancers and regulates tumorigenesis through numerous pathways." (PMID 32164540, 2020). "Yy1 is a well-known TF that governs metabolic programs related both to embryonic stem cell development and cancer initiation." (PMID 32927726, 2020). "Now, the key role of YY1 transcription factor in the suppression of invasion and metastasis has been reported in cancer cells (and references therein)." (PMID 32033023, 2020). "Herein, we summarize recent progress with respect to YY1 and its biological implications in the context of hallmarks of cancer." (PMID 32226547, 2020). "Proteomics identified YY1 as a regulatory factor involved in cancer stem cell (CSC) maintenance across 17 different cancer types." (PMID 33102493, 2020). "Overall, the fact that a single protein, YY1, regulates several hallmarks of cancer indicates the relevant role of YY1 in tumorigenesis." (PMID 32226547, 2020). "The transcription factor, YY1, has also been shown to regulate immune resistance by modulating the expression of PD-L1 in cancer cells through several crosstalk pathways." (PMID 31533363, 2019). "Family with sequence similarity three member C (FAM3C) (interleukin‐like EMT inducer [ILEI]), heat shock factor 1 (HSF1) and Ying‐Yang 1 (YY1) have been independently reported to be involved in the pathogenesis of various cancers." (PMID 30887707, 2019). "Depending on its interacting partners (Protein-Protein Interaction-PPI), promoter environment and chromatin structure, YY1 was shown to regulate several genes that are involved in various homeostatic processes and diseases including cancer." (PMID 31824839, 2019). "Collectively, it is clear that YY1 plays a central role in embryonic development in addition to its role in cancer." (PMID 31824839, 2019). "Extensive evidence indicates that YY1 is an oncogene in various cancers, such as colorectal, prostate and breast cancer." (PMID 31799179, 2019). "YY1 has been demonstrated to induce EMT of cancer cells, having potential as a novel prognostic biomarker for EMT and/or therapeutic target for prevention of metastasis." (PMID 31703732, 2019). "Most processes mediated by YY1 are cancer-related, strongly implicating its importance in cancer development and progression." (PMID 30737378, 2019). "Specifically, three potential binding sites for YY1 were found on a lincRNA involved in occurrence and progression of human cancers." (PMID 31561604, 2019). "In this review, we describe YY1 structure, function, and its protein-protein interactions (PPIs) in the context of gene regulation and various cancers." (PMID 31824839, 2019). "The abnormal expression of YY1 contributes to several human cancers and correlates with poor prognosis." (PMID 31623640, 2019). "ANRIL itself has been also shown to regulate the inflammatory response by its interaction with the YY1 (Yin Yang 1) protein, a transcription repressor involved in cancer development and immune processes." (PMID 30906297, 2019). "Aberrant YY1 expression is closely related to diseases, and its overexpression is observed in various cancers including HCC 23-27." (PMID 31695789, 2019).